IL17A (interleukin 17A)
Diseases named in the same sentence as IL17A in open-access papers (continued):
Sharing a sentence is not in itself a finding about the gene and the disease.
bacterial infection (continued). "Moreover, this “early” feature of IL-17C that we found is not surprising, as it is expressed by epithelial cells during bacterial infections at earlier timepoints in disease than IL-17A." (PMID 38407673, 2024). "The correlation of IL-17A- and IFNγ-producing T cells seen in various bacterial infections may be related to the in vivo plasticity of Th17 cells, where cytokine production can switch from predominantly producing IL-17 to IFNγ, thereby resembling Th1 cells." (PMID 39772023, 2024). "IL‐17A and IL‐17F play important roles in host defense against bacterial infections." (PMID 38660962, 2024). "Our data reveal targeting RORγt and IL-17A pathways may offer a promising therapeutic strategy for bacterial infections in neonatal populations." (PMID 39435479, 2024). "Type 3 immunity, is characterized by the key transcription factor retinoic acid-related orphan receptor (RoRγt) and the expression of IL-17A, IL-17F, and IL-22, mainly facing the extracellular bacterial infection and maintaining intestinal epithelial homeostasis." (PMID 39435479, 2024). "To further evaluate Th1 and Th17 responses in mice infected with T4 alone versus PR8/T4, we analyzed expression of IL-17A+CD4+ T cells in lung lymphocytes by intracellular cytokine staining following in vitro stimulation with PMA/ionomycin 6 days after bacterial infection." (PMID 37222516, 2023). "Thus, blockade of IL-17A abrogated the protective effect of prior T4 infection, which indicates that protection against secondary bacterial infection induced by prior Sp infection is dependent on IL-17A." (PMID 37222516, 2023). "However, IL-17A and IL-17F, which share IL-17RA with IL-25, play major roles in the host against bacterial infections." (PMID 36119076, 2022). "However, additional experiments are needed to better characterize the reciprocal regulation of intestinal IL-33 and IL-17A levels during the course of bacterial infection." (PMID 33654214, 2021). "Furthermore, IL-17A participates in the primary responses to fungi and also bacterial infections and induction of the pro-inflammatory based diseases." (PMID 30984145, 2019). "In many extracellular bacterial infections, IL-17A modulates neutrophil activity by inducing production of cytokines that promote neutrophil expansion and survival (G-CSF and GM-CSF) in addition to chemokines that induce neutrophil recruitment (CXC chemokines)." (PMID 26379269, 2015). "Evidence for TH17-like activities in fish has been provided in the sequencing and characterization of four IL-17 genes, all of which have been shown to respond to bacterial infection and other immune insults, with trout IL17A/F2a demonstrating pro-inflammatory activity." (PMID 23865616, 2013). "The observation that IL-17A did not influence pDC responses would relate to the fact that this cytokine is typically associated with bacterial infections for which strong pDC responses are less relevant." (PMID 23577175, 2013). "IL-17A and IL-17F are able to induce proinflammatory cytokines, chemokines and antimicrobial peptide expression, as well as to promote neutrophil recruitment and provide mucosal host defenses against fungal and bacterial infections." (PMID 22675469, 2012). "TH17 cells release IL-17A at the site of inflammation, leading to an increase in pro-inflammatory cytokines as well as antimicrobial peptides such as β-defensin-256,57, thereby supporting early protective immune responses necessary to combat bacterial infections." (PMID 39794305, 2025). "Previous studies have shown IL-17A/F, IL-17B, IL-17C, IL-17D and IL-17N could stimulate the expression of proinflammatory cytokines, chemokines and antimicrobial peptides in response to bacterial infection." (PMID 40149405, 2025).
bacterial infection (continued). "In vitro differentiation assays revealed that presence of S. aureus antigens induce the development of IL-17-expressing CD4+ T cells (Th17), and in the serum of septic shock patients IL-17A levels were elevated, indicating that bacterial infections might trigger Th17 immune responses." (PMID 35446923, 2022). "We speculate that the reason why the expression levels of IL-17A increased so much in the spleen is due to the mode of bacterial infection, where V. anguillarum in the earliest phase is sequestered by the spleen and may induce a local immune response similar to the expression pattern of IL-4/13." (PMID 32326041, 2020). "Moreover, there are increased expression pattern for both IFN-γ and IL-17A in PDM which suggested a following immune response after bacterial infection may contribute the deterioration of PDM." (PMID 28182101, 2017). "Interleukin-17 (IL-17) is a cytokine family that signatures T helper 17 (Th17) cell subset and contains six members (IL-17A to IL-17F), among which IL-17A is considered as one of the major proinflammatory cytokines mediating the innate and adaptive immune responses against bacterial infections." (PMID 27057095, 2016). "Serum IL-17A and positivity of anti-SRP antibody, together with aging, disease activity, bacterial infection as well as steroid monotherapy, were significantly correlated with PAH in IIM patients." (PMID 40138866, 2025). "We did not observe a discriminative competence between fungal and bacterial infections for both IL-17A and kynurenine in this study." (PMID 33535593, 2021). "Moxifloxacin per se did not affect the levels of the inflammatory mediators IL-1β, KC (the functional homologue of IL-8 in mice) and IL-17A in the lungs of mice in the absence of bacterial infection." (PMID 25034539, 2014). "Regarding Th17 immunity against bacterial infection, Lgals3−/− mice exhibited normal clearance of C. rodentium, indicated by no obvious differences between WT and Lgals3−/− mice in body weight, bacterial load, colon length, and colonic CD4+ T cells, including CD4+IL17A+ cells and Tregs." (PMID 39504243, 2024). "Taken together, our findings indicate that in the absence of bacterial infection, corrector molecules can reduce the inflammatory profile of CFBE-F508del cells by selectively downregulating the production and secretion of IL-6 and IL-17A." (PMID 41487515, 2025).
immune diseases (98 papers, 2008 to 2026). "IL-17a expression has been implicated in many immune diseases and inflammatory responses." (PMID 35739834, 2022). "IL-17A may act as a potential early marker of maternal immune dysfunction and if validated would aid screening of high risk infants to support focused early therapeutic intervention in infancy." (PMID 34505185, 2022). "Similarly, while earlier studies have reported a decreased Faecalibacterium abundance in several immune disorders, we found that a high F. prausnitzii abundance is associated with decreased expression of proinflammatory cytokine IL-17A among healthy children." (PMID 33055153, 2020). "These EDCs disrupt the normal functioning of hormones in males and elevate the levels of pro-inflammatory cytokines such as IL-1b, IL-2, IL-6, IL-10, and IL-17A, leading to immune system disorders." (PMID 39636940, 2024). "It is considered to be a T cell-dependent immune disease whose pathogenesis is influenced by cytokines, such as IL-10, IL-17A, IL-17RA, IL-23A and IL-23R." (PMID 34945130, 2021). "It was further shown that monoclonal antibodies against C-X-C motif chemokine 10 (CXCL-10 or IP-10) or interleukin 17A (IL-17A), used to treat immune system diseases, were able to ameliorate ALI induced by swine-origin influenza A H1N1 in mice." (PMID 32176725, 2020). "The level of IL-17A was increased above the highest observed level in control subjects of 40 pg/ml in 64% of sALS patients, 75% fALS patients, 100% subjects with immune disorders and 0% normal controls (p = 0.003 sALS vs. healthy controls)." (PMID 21062492, 2010). "In addition, mice with knock out of IL-17RA and RC, which are receptors for IL-17A and F, respectively, are highly sensitive to the immune disease, Graft-vs.-host disease (GVDH)." (PMID 32256492, 2020). "Interleukin-17A (IL-17A) is a principal driver of multiple inflammatory and immune disorders." (PMID 27527709, 2016). "IL-17a plays an important role in chronic inflammation, auto-immune diseases, and immune rejection." (PMID 25503995, 2014). "Thirdly, the reprogrammed M2-type macrophage could secrete CCL9 to recruit and stimulate Th17 cells to secrete IL-17A thus aggravating immune disorder, and simultaneously stimulate Tgf-β to activate fibroblast and further differentiated into myofibroblasts aggravating IPF damage." (PMID 38250161, 2024). "Furthermore, we found that levels of salivary IL-6, IFN-γ, IL-10, IL-17A, and TNF-α in OLP patients were significantly upregulated, likely because of the oral immune disorder." (PMID 28400582, 2017). "The increases in the proinflammatory cytokines IL-1a, IL-8, IL-17A, IL-12p40, TNF-β, MCP-1, IL-2, and IL-12p70 and the anti-inflammatory cytokines IL-10 and IL-13 observed in AD patients in our study are consistent with prior evidence of immune dysfunction in AD." (PMID 39346576, 2024).
infectious disease (88 papers, 2006 to 2026). A disorder directly resulting from the presence and activity of a microbial, viral, or parasitic agent in humans. "The cytokine IL-17A has been implicated as an important effector cytokine in various CNS autoimmune and infectious diseases as well as in neurodegenerative processes." (PMID 23468966, 2013). "Although in humans IL-17F and IL-17A are encoded by genes that are located in the same chromosomal region (6p12) there is evidence for differences in gene regulation and expression of both isoforms in the context of infectious diseases." (PMID 33322218, 2020). "The current understanding of IL-17A is that it is critical in inflammation and acting against infectious disease." (PMID 39235230, 2024). "In infectious diseases, IL-17A participates in the innate immune response of the host by inducing cytokines and chemokines to differentiate and migrate granulocytes." (PMID 36860878, 2023). "While co-production of IFN-γ, TNF-α and IL-2 by T cells is frequently investigated, reports on these cytokines in combination with IL-17A in the context of infectious diseases are rather scarce." (PMID 33584671, 2020). "Recent progress in studies of IL-17A cytokine has revealed its important role in protective mechanisms against infectious diseases and in studies of BCG-induced immunity." (PMID 26840977, 2016). "Besides, IFN-ɣ, CD4+ T-cells also demonstrated to be the main source of IL-17A, a key cytokine in the development of a Th17 immune response, which has been implicated in autoimmune and autoinflammatory diseases, but also has proven to be significant in overcoming several infectious diseases." (PMID 26352261, 2015). "In addition, another significant “innate-like” T cell subset comprise MAIT cells, which is recognized for expressing high levels of IL-17A in a variety of infections and non-infectious diseases." (PMID 39192975, 2024). "Thus, the cross talk between TLR3 and IL-17A signaling via TICAM-1 is expected to be important to understand the pathogenesis of those serious infectious diseases, including recent coronavirus disease 2019." (PMID 34819358, 2022). "Nevertheless, due to the osteolytic effect of cytokines such as IL-17A, it may be expected that immunotherapeutic strategies aimed at modulating IL-17 should be carefully considered in the context of infectious disease." (PMID 34240122, 2021). "Although IL17A is associated with the immunological control of various infectious diseases, its role in host response to Eimeria infections is not well understood." (PMID 24571471, 2014). "IL-17A has been identified as a key player in providing protective immunity against intracellular pathogens, as well as at mucosal surfaces, and may be critical for vaccine-induced memory responses against infectious disease." (PMID 36656850, 2023). "Moreover, IL-17A was also involved in the immunopathogenesis of IAV-induced acute lung injury, which was relevant to disease severity and dysregulation of IL-17A could lead to susceptibility to infectious diseases." (PMID 34447853, 2021). "Thus, IL-17A does not play the same role in different infectious diseases." (PMID 33879639, 2021).
cardiovascular diseases (85 papers, 2009 to 2025). "Elevated IL-17A levels are associated with cardiovascular disease and are a key factor in AS development." (PMID 40276600, 2025). "Clinical trials have demonstrated that IL-17A has a stronger association with plaque vulnerability and cardiovascular diseases compared with other cytokines." (PMID 36133421, 2022). "Interleukin (IL)-17A, a potent pro-inflammatory cytokine, has been implicated in the development of a number of cardiovascular diseases." (PMID 25955429, 2015). "A tight coregulation with the miR-206/133b cluster induces proinflammatory cytokine IL-17A in lymphocytes; moreover, miR-133b was found in inflammatory microvesicles in association with metabolic and cardiovascular diseases." (PMID 25594007, 2014). "Given that IL-17A has been demonstrated to be tightly linked to the development of cardiovascular diseases, these data imply the possibility of IL-17A mediating the cardiovascular sequelae of RSDS." (PMID 41180499, 2025). "The role of genetic knockout mouse models of IL-17A and IL-17RA in cardiovascular diseases has been investigated in literature." (PMID 40276600, 2025). "IL-17A is highly significant, as it has been shown to directly contribute to the pathogenesis of cardiovascular diseases including hypertension." (PMID 41180499, 2025). "IL-17A is a cytokine involved in inflammation, with a known role in cardiovascular diseases through its impact on vascular inflammation and myocardial remodeling." (PMID 40599146, 2025). "A particularly important cytokine in the development of cardiovascular diseases is IL-17A, which is mainly produced by Th17 cells." (PMID 35326095, 2022). "Recent studies have highlighted the role of IL-17A in connecting cardiovascular disease (CVDs) with psoriatic inflammation, suggesting that anti-IL-17A therapy could not only benefit skin conditions but also reduce cardiovascular inflammation." (PMID 40064794, 2025). "In addition, increased circulating levels of IL-17A have been reported in several cardiovascular diseases." (PMID 38132456, 2023). "Recent evidence indicated that IL-17A may represent one of the main links between cardiovascular disease manifestations and psoriatic inflammation." (PMID 32010143, 2019). "Based on the findings, IL-17A might serve as a useful indicator for heart-related illnesses, as individuals with lower IL-17A levels in their blood had a higher chance of developing cardiovascular diseases." (PMID 39844544, 2025). "We demonstrated that the non-traditional cardiovascular risk factors, the TG/HDL ratio, IL-2, IL-6, IL-17A, and INF-γ, were significantly increased in children with MetS than those without MetS, and may therefore be used as biomarkers to predict future cardiovascular disease." (PMID 37892418, 2023). "This study suggests that IL-17A may be a potential therapeutic target for cardiovascular diseases." (PMID 36133421, 2022). "Regarding the use of these mouse models in studies on CMs, there was not explicitly mentioned that have utilized IL-17A or IL-17RA genetic knockout mouse models specifically for investigating the effects of CMs on cardiovascular diseases." (PMID 40276600, 2025). "IL-17A stimulates cardiac fibroblast proliferation, a component of the pathway resulting in cardiac fibrosis, and is of interest in the consideration of GCR-induced cardiovascular disease." (PMID 37099482, 2023). "We demonstrated that the TG/HDL ratio, IL-2, IL-6, IL-17A, and INF-γ were significantly greater in subjects with MetS than in those without MetS, and may therefore be used as biomarkers to predict future cardiovascular disease." (PMID 37892418, 2023).
metabolic disorders (48 papers, 2014 to 2026). "Both IL-17A and IFN-γ are considered proinflammatory contributors in the pathogenesis of metabolic disorders." (PMID 36781473, 2023).
kidney diseases (44 papers, 2010 to 2025). "We did not observe any relationship between the selected SNPs in genes coding for IL-17A, IL-17RA, IL-17RC, and miR-146a-5p and kidney disease risk, as their alleles/genotypes segregated similarly in patients and controls." (PMID 38792460, 2024). "Extensive research has implicated Th17 cells and IL-17A in the pathogenesis of a spectrum of renal disorders." (PMID 39656542, 2024). "It has been shown that complement synthesis is closely associated with the development and progression of renal disease and that C3 secreted by macrophages leads to IL-17A-mediated inflammatory cell infiltration in renal tissue." (PMID 34424825, 2021). "The role of Th17 cells and their primary effector cytokine, IL-17A, in the genesis of diverse renal disorders has increasingly come under scrutiny." (PMID 39656542, 2024). "In the last several years, there has been an increasing number of reports indicating enhanced TH17/IL-17A activation in human kidney disease, while several studies in animal models point to an important role for TH17 cells in kidney disease progression." (PMID 35422004, 2022). "IL-17A has been reported to be a vital inflammatory factor and involved in several different kidney diseases 56-58." (PMID 33391465, 2021). "Th17 immune cells and their effector cytokine IL-17A have recently emerged as promising targets in several clinical conditions, including renal diseases." (PMID 31963845, 2020). "Many studies described the IL-23/IL-17A pathway as a novel therapeutic target against chronic inflammatory diseases, including renal disease with different etiologies." (PMID 31963845, 2020). "IL-17A has emerged as an important inflammatory mediator involved in the genesis of immune and chronic inflammatory diseases, including cardiovascular and renal diseases, and diabetic complications, as described in this review." (PMID 31963845, 2020). "Interestingly, circulating IL-17A levels are related to the severity of kidney disease and progressively decrease from subjects with normal glucose tolerance to subjects with type 2 diabetes with and without DN." (PMID 31963845, 2020). "Whether higher doses or longer exposure to IL-17A results in kidney disease should be addressed in future studies." (PMID 31572188, 2019). "The systemic IL-17A infusion in C57BL/6 mice increased blood pressure and promoted the recruitment of inflammatory cells into the kidney, but, at the dose and time-points studied, this did not result in biochemical or histological evidence of kidney disease beyond inflammation." (PMID 31572188, 2019).